ASB7 (ankyrin repeat and SOCS box containing 7)
Description:
Substrate-recognition component of a cullin-5-RING E3 ubiquitin-protein ligase complex (ECS complex, also named CRL5 complex), which mediates the ubiquitination and subsequent proteasomal degradation of target proteins, such as LZTS1, PSRC1 and SUV39H1. The ECS(ASB7) complex acts as a negative regulator of H3K9me3 histone mark by mediating ubiquitination and degradation of SUV39H1: ASB7 is recruited to heterochromatin by CBX5 (HP1 alpha), where it associates with SUV39H1, promoting the ubiquitin-proteasome-mediated degradation of SUV39H1. During mitosis, ASB7 is phosphorylated and inactivated, allowing SUV39H1 activity. The ECS(ASB7) complex also plays a role in spindle dynamics and genome integrity by targeting the mitotic progression protein PSRC1 for proteasomal degradation in a cell cycle-dependent manner. Also participates in meiosis by mediating the proper attachment between kinetochores and microtubules (By similarity).
Tractability: PROTAC: ubiquitination databases record sites on it.
Gene: Protein-coding gene on chromosome 15 (100,602,547 to 100,651,703, forward strand). Ensembl gene ENSG00000183475.
Subcellular location: Chromosome; Nucleus
Subcellular location (Human Protein Atlas): Golgi apparatus; Vesicles; Nucleoplasm
Pathways (Reactome):
Immune System: Antigen processing: Ubiquitination & Proteasome degradation
Metabolism of proteins: Neddylation
Gene Ontology:
Molecular function: protein binding; ubiquitin-like ligase-substrate adaptor activity
Biological process: proteasome-mediated ubiquitin-dependent protein catabolic process; regulation of heterochromatin organization; intracellular signal transduction; protein ubiquitination
Cellular component: chromosome; Cul5-RING ubiquitin ligase complex; heterochromatin; cytosol; nucleus
Genetic constraint (gnomAD): Loss-of-function variants: 4 observed, 33.06 expected, observed/expected ratio (o/e) 0.12, 90% interval 0.059 to 0.28. The upper end of that interval is the gene's LOEUF score, 0.28, which puts it in group 1 of 6, group 1 being the genes least tolerant of losing a copy. Missense variants: 181 observed, 422.79 expected, observed/expected ratio (o/e) 0.43, 90% interval 0.38 to 0.48. Synonymous variants: 172 observed, 162.53 expected, observed/expected ratio (o/e) 1.06, 90% interval 0.93 to 1.2.
Homologues: Orthologues: chimpanzee ASB7 (100% identical), dog ASB7 (100% identical), guinea pig ASB7 (100% identical), macaque ASB7 (100% identical), mouse Asb7 (99% identical), rabbit ASB7 (99% identical), tropical clawed frog asb7 (96% identical), zebrafish asb7 (92% identical), pig ASB7 (87% identical), rat Asb7 (86% identical). Paralogues in human: ANK2 (38% identical), ANK3 (34% identical), ANK1 (33% identical).
Diseases named in the same sentence as ASB7 in open-access papers:
ASB7 is named in the same sentence as 4 diseases in open-access papers, as found by Europe PMC text mining. Sharing a sentence is not in itself a finding about the gene and the disease. The quoted sentences say what the papers report.
aneuploidy (1 paper, 2020). Chromosomal disorder consisting of the presence a chromosomal abnormality in which there is an addition or loss of chromosomes within a set. "Correspondingly, the aneuploidy incidence in aged oocytes was significantly lowered when ASB7 expression was elevated." (PMID 33251222, 2020).
tumor (1 paper, 2026). "Here, we report that ASB7 promotes tumor cell protrusion formation, invasion, migration, and lung metastasis." (PMID 42086529, 2026).
ASB7 also shares sentences with these, for which no sentence is quoted: cerebral malaria (1 paper); osteosarcoma (1).